FH (fumarate hydratase)
Diseases named in the same sentence as FH in open-access papers (continued):
Sharing a sentence is not in itself a finding about the gene and the disease.
viral infections (1 paper, 2025). "Together, these findings suggest that fH may contribute to immune surveillance, particularly under conditions of impaired peptide loading, such as in some viral infections." (PMID 41067637, 2025).
vitamin D deficiency (1 paper, 2023). A nutritional condition produced by a deficiency of VITAMIN D in the diet, insufficient production of vitamin D in the skin, inadequate absorption of vitamin D from the diet, or abnormal conversion of vitamin D to its bioactive metabolites. "This unreported increased occurrence of CLs and DFs in FH non-mutated patients with symptomatic ULs with vitamin D deficiency suggests a potential pathogenetic role of vitamin D bioavailability also for CLs and DFs." (PMID 37606484, 2023).
tumor (319 papers, 2002 to 2026). "For instance, succinate accumulation in SDH-deficient tumors can silence tumor suppressor genes via hypermethylation, while fumarate accumulation in FH-deficient tumors has been linked to silencing of neuroendocrine differentiation genes." (PMID 40931345, 2025). "Mutations of SDH and FH (both tumor suppressors) are loss-of-function mutations and cause abnormal accumulation of succinate and fumarate, which promotes tumor growth and development." (PMID 40863132, 2025). "Subsequently, further immunohistochemistry was performed, which proved tumour cells with fumarate hydratase deficiency." (PMID 40264827, 2025). "FH mutations have been detected in numerous tumor entities, most notably in HLRCC, a syndrome defined by a spectrum of benign and malignant neoplasms." (PMID 41374387, 2025). "It is a rare autosomal dominant disorder caused by a mutation in the fumarate hydratase, a tumor suppressor gene, leading to an accumulation of fumarate." (PMID 40065881, 2025). "Preclinical biological validation was undertaken in fumarate hydratase‐deficient murine tumor models and controls." (PMID 40331406, 2025). "Fumarate accumulation due to FH deficiency in tumor cells results in epigenetic alterations such as DNA hypermethylation." (PMID 40931345, 2025). "Fumarate-mediated PTEN succination leads to PTEN inactivation and consequently activation of the PI3K-AKT axis to promote FH-deficient tumor cell proliferation." (PMID 41427347, 2025). "Loss-of-function mutations in tumor suppressors such as FH or SDH are challenging to target, while targeting gain-of-function mutations such as those found in IDH is much more feasible." (PMID 40863132, 2025). "Both MCUL and HLRCC have been shown to arise from heterozygous germline mutations in the fumarate hydratase (FH) gene, which is thought to act as a tumor suppressor gene under normal conditions." (PMID 39201746, 2024). "The presence of S-(2-succino)-cysteine residues can be detected by immunohistochemistry and serves as a marker of tumor FH deficiency along with the alterations of FH expression and FH gene mutations." (PMID 38390862, 2024). "The presence of FH deficiency in the tumor was estimated by IHC staining of two markers: FH and 2SC." (PMID 38721148, 2024). "FH acts as a tumor suppressor gene that encodes fumarate hydratase, which is an enzyme that catalyzes the conversion of fumarate to malate in the Krebs cycle." (PMID 39160519, 2024). "Loss of heterozygosity analysis revealed the loss of the wild-type allele of the FH gene in the tumor." (PMID 38721148, 2024). "Tumor tissues consistently exhibit a loss of heterozygosity at the FH locus, resulting in a complete loss of FH enzymatic function." (PMID 38793008, 2024). "This case highlights the association between HNPGLs and hereditary FH mutations and firmly supports its consideration as a tumor susceptibility gene." (PMID 38721148, 2024). "This demonstrates the potential pathogenic effect of the FH p.S249R variant and the presence of FH deficiency in the tumor." (PMID 38721148, 2024). "Whole-exome sequencing of tumor and matched bloodDNA detected a somatic FH-inactivating variant, c.1043G>C(p.Gly348Ala), and a pathogenic germline FH variant,c.349G>C (p.Ala117Pro), respectively." (PMID 39705504, 2024). "Tumor development in heterozygous FH mutation carriers involves somatic inactivation of the remaining copy of the gene." (PMID 38390862, 2024). "Extensive research over the past two decades has shed light on the molecular pathways influenced by FH inactivation, paving the way for targeted treatment approaches aimed at FH-deficient tumor cells." (PMID 38793008, 2024). "Prior to the molecular characterization of HLRCC tumors, targeted therapies for this aggressive tumor type primarily focused on the metabolic changes caused by FH inactivation." (PMID 38793008, 2024).
tumor (continued). "Several studies have reported new sights on this kind of tumor, both clinically and in scientific research, however, the potential involvement of LncRNA is poorly defined in FH-deficient RCC." (PMID 38374146, 2024). "For instance, the ability to image fumarate at the single cell level with this method will help to appreciate the intracellular heterogeneity and clonality of FH-deficient cells or tumour tissues." (PMID 38918386, 2024). "Similar to our case, the tumor showed positive FH and 2SC staining and carried a pathogenic/likely pathogenic FH: p.Thr234Ala variant." (PMID 38721148, 2024). "Simultaneously, the tumor showed positive diffuse cytoplasmic staining for 2SC, a marker of deficient FH activity." (PMID 38721148, 2024). "Loss of FH protein in the tumor cells was confirmed by IHC in patient 4, with validation performed on the same day clinical laboratory control sample." (PMID 39351526, 2024). "IHC analysis of FH-deficient RCC showed that GGT1 was expressed in the tumor cells, whereas DPEP1 was primarily confined to the normal adjacent tissues." (PMID 37053010, 2023). "It would also be important to understand why FH loss gives rise to such a unique set of tumours, affecting different tissues with different malignancy." (PMID 37689804, 2023). "Fumarate hydratase–deficient (FH-deficient) RCC is a recently described unique subtype of RCC characterized by germline or somatic ablation of FH, with a coinciding somatic hit that affects the second FH allele in the tumor." (PMID 37053010, 2023). "Venn diagram analysis identified 4 metabolites that characterize FH deficiency–associated phenotypes that also correlate with tumor burden." (PMID 37053010, 2023). "Considering the relevance of the TCA for cell survival, it was surprising that FH loss was not only tolerated by the cells but also that it led to the development of tumours in HLRCC patients." (PMID 37689804, 2023). "On the other hand, a tumour-suppressing role has also been proposed for fumarase in human cells, owing to FH mutations, which predispose individuals to common types of tumour." (PMID 37686461, 2023). "The FH gene, previously suggested as a tumor-suppressor gene candidate in 1q-deleted NB, encodes fumarate hydratase and is involved in non-homologous end-joining repair, promoting DNA repair through the inhibition of histone H3 demethylation." (PMID 38136279, 2023). "As mentioned in the previous sections, the role of FH loss and fumarate on the immune system, as well as other components of the tumour microenvironment, need further investigation." (PMID 37689804, 2023). "Pollard and colleagues described the same phenomenon in SDH- and fumarate hydratase (FH)-mutated Pheo/PGLs, that indeed, are characterized by 25-fold higher succinate levels than tumours mutated in the other susceptibility genes." (PMID 37033265, 2023). "In particular, suc-cys, suc-cys-gly, suc-ado, fumarate, and creatine-riboside were identified as potential biomarkers for monitoring the status and tumor burden of patients with FH variants." (PMID 37053010, 2023). "As with CDXs, suc-ado, suc-cys, and suc-cys-gly were particularly detected in the mice with FH-deficient PDXs and proportionally increased over time along with tumor growth." (PMID 37053010, 2023). "For instance, how FH-deficient cells influence the tumour microenvironment and communicate with surrounding cells, possibly shaping immunity and inflammation will be a very important future line of investigation." (PMID 37689804, 2023). "Germline mutations in the FH gene are also correlated with an increased risk of tumorigenesis, which indicates FH is a tumor suppressor." (PMID 37592347, 2023). "Fumarate hydratase (FH) mutation or inactivation will lead to the accumulation of fumaric acid in cancer cells and promote the proliferation of tumor cells." (PMID 38139250, 2023).
tumor (continued). "In particular, two tumour-derived metabolites, succinyl-adenosine and succinic-cysteine were found to faithfully reflect FH mutation status and tumour mass." (PMID 37689804, 2023). "FH-deficient RCC arises in the setting of germline, or solely somatic, mutations in the FH gene, a two-hit tumor suppressor gene." (PMID 37259915, 2023). "The loss of FH and the accumulation of fumarate elicit the pro-oncogenic signals which contribute to the transformation of normal cells into tumor cells." (PMID 36778129, 2023). "In conclusion, the recent discoveries underpinning the role of FH loss in cancer open new therapeutic strategies to treat more efficiently these tumours and enable us to have a better understanding of the biology behind this rare cancer." (PMID 37689804, 2023). "FH loss can predispose to cancer and has been observed in other tumour types, such as paraganglioma and pheochromocytoma, adrenocortical carcinoma, neuroblastoma, glioma, ependymoma, osteosarcoma and Ewing’s sarcoma." (PMID 37689804, 2023). "It was reported that FH-deficient human tumors have an increased hypoxia-inducible factor (HIF) activity that contributes to rapid tumor growth and proliferation." (PMID 35163394, 2022). "FH was identified as a tumor suppressor due to the lower enzyme activity or deficiency in tumors from patients with HLRCC." (PMID 35163394, 2022). "There are no detailed data describing the immunological compartments of tumor microenvironments in FH-deficient cells; however, a recently published study analyzed tumor-infiltrating lymphocytes in cancer patients with FH deficiency." (PMID 35205136, 2022). "Additional Sanger sequencing analysis of the FH variant using blood- and tumor-derived DNA showed that the mutant allele was predominant in the tumor, suggesting loss of heterozygosity (LOH)." (PMID 35034951, 2022). "Fumarate hydratase (FH), a TCA cycle enzyme, has been shown to be a tumor suppressor and FH loss of function confers cancer cells resistance to ferroptosis." (PMID 34784264, 2022). "This was posited to be an underlying mechanism of its tumor suppressive function, wherein the loss of function mutation in FH results in tumor growth benefits." (PMID 35065965, 2022). "Succinate dehydrogenase (SDH), which converts succinate into fumarate, and fumarate hydratase (FH), which converts fumarate into malate, potentially function as tumor suppressors, since they tend to gain loss-of-function mutations." (PMID 33747521, 2021). "Firstly, fumarate can accumulate to millimolar levels in FH-deficient tumor cells, and high fumarate levels can alter multiple enzymatic reactions in which fumarate is directly involved as either a substrate or product." (PMID 35006438, 2021). "FH has been reported to be associated with tumorigenesis, specifically by altering the gene expression and configuration of tumor cells." (PMID 34243715, 2021). "FH inactivation was confirmed to be associated with the initial tumor-promoting event in HLRCC, leading to decreased FH enzyme function." (PMID 34113573, 2021). "This phenotype seems to be involved in tumor progression and mutations in the FH, SLC25A11, and MDH2 genes along with SDHB and SDHD mutations can be considered to be a risk factor for PPGL malignancy." (PMID 34833055, 2021). "The same mass spectrometry-based assay has identified rare cases of tumours with SDHx and FH mutations, which are caused predominantly by germline mutations." (PMID 34822422, 2021). "This feature is underpinned by tumor biology, as the FH-deficient cells have lost their ability to perform oxidative phosphorylation through the Krebs cycle, therefore depending on glycolysis, which is the basis of the Warburg effect in FDG PET imaging." (PMID 33608050, 2021). "HLRCC is caused by germline mutations in the fumarate hydratase (FH) gene, which encodes an enzyme involved in the tricarboxylic acid cycle with a tumor suppressor role." (PMID 34445194, 2021).
tumor (continued). "Cluster 1A Krebs cycle-related tumours are secondary to mutations in SDHx, FH, MDH2, GOT2, SLC25A11, DLST or IDH1/2." (PMID 34834591, 2021). "ROS involved in tumor formation accumulates in tumors with FH-deficient, and high levels of ROS cause the accumulation of HIFα." (PMID 34113573, 2021). "In a first stage, the inability to produce fumarate near the nucleus impairs DNA damage repair and accounts for accumulation of mutations, then the proliferation of FH deficient cells leads to accumulation of fumarate that supports tumor progression." (PMID 33233657, 2020). "In 2011, it was demonstrated that NRF2 hyperactivation is a driving mechanism of tumor progression in PRCC featuring FH deficiency." (PMID 33233657, 2020). "Succination induced by FH-deficiency led to inhibition of mitochondrial respiration, activated antioxidant response, and tumor growth." (PMID 32799884, 2020). "Tumor-only variant calling for small genetic variants using a somatic variant caller identified a single SNV/indel in the FH gene in 8/13 (61.5%) of ULs." (PMID 32612247, 2020). "Together with the low VAF of the SNV in this sample, this observation points to the explanation of tumor-heterogeneity in this UL with multiple second-hit events occurring after an initial deletion of one FH allele." (PMID 32612247, 2020). "The theory that fumarate is defined as an oncometabolite is derived from studies that analyzed the consequences of fumarate hydratase deficiency, leading to accumulation of fumarate and tumor progression in various cancers." (PMID 32640711, 2020). "The metabolic shift of FH-deficient tumor cells to aerobic glycolysis also leads to increased reactive oxygen species (ROS) levels." (PMID 31804603, 2019). "We previously found increased Nrf2 expression and aerobic glycolysis in HLRCC tumor cells with FH mutation." (PMID 31752777, 2019). "Mutations involving SDHx or FH lead to DNA hypermethylation, explaining both the tumor-suppressive role of these genes and the phenotypic characteristics." (PMID 31205467, 2019). "GLS and GLS2 are respectively indirect and direct downstream targets of c-Myc35 and were significantly overexpressed in FH-deficient tumor specimens." (PMID 31804603, 2019). "In 2013, a germline mutation in FH was found in a patient with PCC by whole exome sequencing (WES) applied to a tumor displaying transcriptional and methylation (CIMP profile) similarities to SDH-mutant tumors." (PMID 31100940, 2019). "Others tumor suppressors, such as the loss of function of FH (fumarate hydratase), SDH (succinate dehydrogenase) or VLH can lead to a pro-tumorigenic role." (PMID 30708988, 2019). "Mutations in the FH gene stimulate the development of tumor LM in case of its biallelic inactivation; the mutative rate of this gene in patients that suffered from LM is 10.5% with biallelic loss of FH." (PMID 31817606, 2019). "FH is a classic tumor suppressor gene, since all tumors caused by mutations in this gene exhibit somatic loss of the wild-type allele." (PMID 31817606, 2019). "The inherited form of the more aggressive, type II pRCC tumours is caused by germline mutation of the gene encoding fumarate hydratase (FH)." (PMID 30099580, 2018). "FH is a tumor suppressor gene in the TCA cycle that encodes FH enzyme, which converts fumarate into malate." (PMID 30538672, 2018). "Both SDH and FH are classical tumor suppressor genes, and predispose individuals with heritable mutated genes to cancer when the second wild-type allele is lost." (PMID 28748451, 2018). "We have recently shown that the accumulation of fumarate in FH-deficient tumour drives an epigenetic reprogramming that contributes to tumour invasiveness." (PMID 27886164, 2017). "Affected individuals harbor a germline heterozygous loss-of-function mutation of the Krebs cycle enzyme, fumarate hydratase (FH) gene, which acts as tumor suppressor." (PMID 27819754, 2017).